SMYD3 (SET and MYND domain containing 3)
Diseases named in the same sentence as SMYD3 in open-access papers (continued):
Sharing a sentence is not in itself a finding about the gene and the disease.
cancer (continued). "As for its role in cancer progression, SMYD3 has been described as a core promoter of cell cycle regulation that is involved in phase transition and allows cancer cells to bypass signals of cell cycle arrest, thereby contributing to uncontrolled proliferation." (PMID 34503239, 2021). "SMYD3 mediates the progression of several cancer types by regulating oncogenic mechanisms and signaling pathways in different ways." (PMID 34503239, 2021). "SMYD3 has been reported to function in key pathways for self-renewal and tumorigenicity of GC stem cells through activation of the cancer stem cell transcription factor ASCL2." (PMID 33637115, 2021). "We first describe the oncogenic activity of SMYD3 as a transcriptional activator of genes involved in tumorigenesis, cancer development and transformation and as a co-regulator of key cancer-related pathways." (PMID 34503239, 2021). "A previous work found that human cancer cells express a cleaved form of the SMYD3 protein that lacks the first 34 amino acid residues in the N-terminal region where the SAM-binding pocket is located." (PMID 34281237, 2021). "SMYD3 can promote cancer by co-regulating the activation of major cancer-related pathways and can act as a critical driver in tumorigenesis." (PMID 34503239, 2021). "In this light, in-depth studies of the functional role of SMYD3 and its overexpression in cancer are instrumental to elucidate the mechanism by which it regulates oncogenic progression." (PMID 34503239, 2021). "While high levels of SMYD3 have been positively correlated with cancer progression in cellular and advanced mice models, suggesting it as a potential risk and prognosis factor, its activity seems dispensable for autonomous in vitro cancer cell proliferation." (PMID 34503239, 2021). "Most of the studies performed to date showed a correlation between SMYD3 overexpression and cell growth in cancer settings." (PMID 34503239, 2021). "In the next section (“Cancer Implications”) we will review the implications of these SMYD3 substrates in cancer development and progression." (PMID 33637115, 2021). "In detail, we will discuss SMYD3 activity in orchestrating DNA damage checkpoint dynamics, driving cell cycle phase transition, and supporting genomic protection of cancer cells." (PMID 34503239, 2021). "In a previous paper, we reported that RNA interference (RNAi)-mediated SMYD3 ablation impairs CRC cell proliferation, suggesting that SMYD3 is required for proper cancer cell growth." (PMID 34503239, 2021). "Growing evidence seems to confirm that SMYD3 overexpression correlates with poor prognosis, cancer growth and invasion, especially in gastrointestinal tumors." (PMID 34503239, 2021). "These experiments revealed that SMYD3 is expressed in mESCs and it is detectable in the cytoplasm, nuclei and chromatin fraction, as previously shown for cancer cell lines." (PMID 34069776, 2021). "Despite these deficiencies in our knowledge of its function, current research points to the promise of SMYD3 as a therapeutic target in the treatment of cancer." (PMID 33637115, 2021). "SMYD3 is the most important member, as several findings have demonstrated its role in tumor cell growth and its increased expression in various cancers." (PMID 32071406, 2020). "In conclusion, we have successfully used in silico compound screening to identify a small molecule that inhibit SMYD3 activity in vitro and reduced cancer cell growth and proliferation." (PMID 33333978, 2020). "In fact, SMYD3 is localized in the cytoplasm in many tumor cells, but a fraction of the protein is also found in the nucleus of several cancer cells." (PMID 31935919, 2020). "In cancer cell lines, SMYD3-mediated methylation of MAP3K2 at lysine 260 enhances activation of the Ras/Raf/MEK/ERK signaling and SMYD3 depletion synergizes with a MEK inhibitor to block Ras-driven tumors." (PMID 32516941, 2020).
cancer (continued). "Overall, these data hint for a clinical role in SMYD3 as a prognostic factor in different forms of cancer." (PMID 31935919, 2020). "Experimental evidences with tumor biopsies and expression analysis of tumor datasets revealed that SMYD3 is over-expressed in various forms of cancer, and that higher SMYD3 levels correlate with a reduced overall survival and worst prognosis." (PMID 31935919, 2020). "SMYD3-mediated methylation of MAP3K2 promoted the activation of the Ras/Raf/MEK/ERK signaling module in cancer cell lines." (PMID 32582175, 2020). "Future work will involve the application of this approach to other therapeutic targets and the continued development and optimization of therapeutics for SMYD3-related cancers." (PMID 33333978, 2020). "In the following sections, we will delve deeper into the diverse SMYD3-mediated functions and their role in cancer progression." (PMID 31935919, 2020). "SMYD3 is also known to regulate cancer cell proliferation and viability through its interaction with vascular endothelial growth factor receptor 1 (VEGFR1) and estrogen receptor (ER), both of which are non-histone proteins." (PMID 33333978, 2020). "We previously reported that telomerase reverse transcriptase (hTERT) and AR were direct targets of SMYD3 in cancers." (PMID 32007952, 2020). "Here, we aim at drawing together several reports addressing SMYD3 function in cancer, as well as the diverse activities in which it is involved." (PMID 31935919, 2020). "SMYD3 is aberrantly over-expressed in the majority of cancers and has been shown to exert oncogenic effects through various mechanisms." (PMID 32007952, 2020). "Our results provide a proof of concept for this fast and affordable small molecule hit-to-lead methodology as well as a promising candidate small molecule SMYD3 inhibitor for the treatment of human cancer." (PMID 33333978, 2020). "Specific inhibition of SMYD3 reduces cancer cell proliferation and migration of cancer cells and induces apoptosis." (PMID 31968646, 2020). "SMYD3 appears to promote cancer in a kaleidoscopic manner, reprogramming both the transcriptional response and modulating signaling pathways, thus orchestrating different oncogenic inputs, which synergize towards tumor transformation." (PMID 31935919, 2020). "The findings analyzed herein demonstrate that a complex network of SMYD3-mediated cytoplasmic and nuclear interactions promote oncogenesis across different cancer types." (PMID 31935919, 2020). "We describe SMYD3-dependent mechanisms affecting cancer progression, highlighting SMYD3 interplay with proteins and RNAs involved in the regulation of cancer cell proliferation, migration and invasion." (PMID 31935919, 2020). "SMYD3 is over-expressed in several cancer types and represents a promising target to treat different malignancies." (PMID 31935919, 2020). "Our study takes SMYD3 beyond cancer functions and links with recent reports implicating SMYD3 as a developmental regulator." (PMID 31754141, 2019). "The SMYD3 protein is frequently overexpressed in human cancers; it recognizes specific DNA sequences and has been reported to act as an epigenetic regulator through tri-methylation of histone residues H3K4, H4K5 and H4K2032–34." (PMID 31754141, 2019). "Appreciation of SMYD3 involvement in signaling would broaden our view of the role of SMYD3 in cancer beyond epigenetic regulation." (PMID 31737645, 2019). "SMYD3 is overexpressed in multiple cancer types, suggesting its essential role in tumor initiation and progression." (PMID 31417652, 2019). "The interaction of SMYD3 with proteins involved in these signaling pathways would provide additional mechanistic links between SMYD3 overexpression and cancers." (PMID 31737645, 2019). "While most of the previous work on SMYD3 has focused on its implication in cancer, its role in normal differentiation programs has been largely ignored." (PMID 31754141, 2019).
cancer (continued). "The invalidation of the published roles for MELK, SMYD2 and SMYD3 suggest that a much higher bar must be set for the use of genetic tools in cancer biology." (PMID 29856759, 2018). "The mRNA and protein expression of EZH2 and SMYD3 in cancer tissues and adjacent tissues were detected by RT-qPCR and Western blotting." (PMID 29089464, 2018). "The results showed that the mRNA and protein expression of EZH2 and SMYD3 in cancer tissues were higher than those in adjacent tissues (P<0.05)." (PMID 29089464, 2018). "SET- and MYND-domain containing protein 3 (SMYD3) is EZH2 target, and H3K4 methyltransferase plays a critical role in various human cancers by activating oncogenes and genes associated with cell-cycle regulation." (PMID 28740569, 2017). "Previous studies have shown that miR-124 inhibits cancer cell invasion and metastasis by targeting other molecules, including slug, Rac-1, SMYD3, SphK1, and ROCK1." (PMID 28270130, 2017). "Three terms indicating the known biological roles of SMYD3 in promoting cancer cell metastasis and invasion were also found: ‘cell–substrate adhesion’, ‘cell–matrix adhesion’, and ‘positive regulation of cell adhesion’." (PMID 28781952, 2017). "In summary, our findings unveiled the novel mechanism of constitutive hyperphosphorylation on AKT1 in cancer cells, mediated by SMYD3-dependent methylation." (PMID 27626683, 2016). "Taken together, these results clearly indicate that SMYD3-mediated Lys 14 methylation on AKT1 must be a good target for anti-cancer treatment." (PMID 27626683, 2016). "Lysine 14-substituted AKT1 shows significantly lower levels of phosphorylation at threonine 308 than wild-type AKT1, and knockdown of SMYD3 as well as treatment with a SMYD3 inhibitor significantly attenuates this phosphorylation in cancer cells." (PMID 27626683, 2016). "In fact, overexpression of SMYD3 is observed in a wide variety of cancer tissues, and inactivation of SMYD3 results in growth suppression of various types of cancer cells." (PMID 27626683, 2016). "In cancer, SMYD3 methylates histone H3 K4 and upregulates a number of oncogenes such as c-Myc, STAT3, and MMP9." (PMID 27790639, 2016). "We knocked down SMYD3 in cancer cells by specific siRNAs and examined phosphorylation status of AKT1." (PMID 27626683, 2016). "A series of studies pointed to the potential involvement of Smyd2 and Smyd3 in various human cancers." (PMID 27655694, 2016). "SET and MYND domain containing protein 3 (SMYD3) is a histone methyltransferase, which has been implicated in cell growth and cancer pathogenesis." (PMID 26350217, 2015). "SMYD3 has been regarded as an important factor in cancer, based on the fact that high level expression of SMYD3 has cell proliferative effects and up-regulates a number of genes involved in cell growth and proliferation." (PMID 26350217, 2015). "This suggests a possible cooperative function of PC4 in SMYD3 transcription network in cancer cells." (PMID 26350217, 2015). "Supporting this idea, our knockdown and rescue experiments provided a clear and convincing demonstration that SMYD3 transactivation of growth/invasion-stimulatory genes in cancer cells is dependent of PC4." (PMID 26350217, 2015). "Dynamic regulation of SMYD3-mediated H3K4me3 by PC4 also contributes to productive transcription of SMYD3 responsive genes in cancer cells." (PMID 26350217, 2015). "More recently, it was demonstrated that methylation of MAP3K2 by the cytosolic KMT SMYD3 promotes tumour formation through activation of the Ras-signalling pathway, establishing a role also for cytosolic lysine methylation in cancer." (PMID 26448330, 2015). "As SMYD3 is often overexpressed in cancer cells, we first examined SMYD3 levels in bladder, breast, colon and prostate cell lines by immunoblotting." (PMID 26350217, 2015).
cancer (continued). "Three bladder (J82, T24 and RT4) and three colon (HCT116, CaCO2 and HT29) cancer cell lines expressed significantly higher levels of SMYD3 compared to their normal counterparts (UROtsa and CCD-18Co)." (PMID 26350217, 2015). "Immunoblot analysis confirmed that stable transfection of SMYD3 shRNA efficiently silenced the expression of SMYD3 in the cancer cells." (PMID 26350217, 2015). "These genes also tend to exhibit higher ratios of expression changes, which is in agreement with the primarily activating function expected for SMYD3 during cancer development." (PMID 26350217, 2015). "It has been known for years that SMYD3 overexpression is related to transcriptional changes in cancer cells, but it is only recently that molecular studies have merged to elucidate the oncogenic actions of this chromatin regulator." (PMID 26350217, 2015). "The recognition of the role of SMYD3 in tumorigenesis has led to studies regarding the effects of the knockdown of SMYD3 in cancer cells." (PMID 24710145, 2011). "Analysis in lymphoblastoid cell lines and functional validation in cancer cell lines suggest the probable role of SMYD3 to AraC and gemcitabine drug response phenotype." (PMID 20525348, 2010). "Members of this family are direct regulators of cancer (Smyd3) and essential developmental processes (Smyd1)." (PMID 16805913, 2006). "Because Smyd3 was elevated in both P12 premalignant mammary epithelial cells and malignant tumor tissues of Brca1MKO mice, we then explored whether elevated SMYD3 levels could affect cancers diagnosed in human PABC." (PMID 40157910, 2025). "In summary, the critical role of the cancer cell‐intrinsic SMYD3‐SREBP1‐CD47 axis is elucidated in regulating the immune microenvironment in ccRCC and provides a potential therapeutic strategy to manipulate the tumor immune milieu in favor of antitumor immunity." (PMID 40548645, 2025). "In summary, in addition to affecting the proliferation of tumor cells themselves, cancer cell‐intrinsic SMYD3 shapes the immunosuppressive microenvironment by altering the landscape of immune cell infiltration, thus impairing the efficacy of ICI therapy (PD‐1 blockade)." (PMID 40548645, 2025). "Finally, ddPCR assays showed that the expression of c-MYC target genes was decreased in PDTOs exposed to EM127, confirming that SMYD3 plays an important role in cancer stemness features also in this complex cellular model." (PMID 40588481, 2025). "Given the limited evidence regarding SMYD3’s role in the mechanisms regulating meiosis, numerous findings confirm its involvement in cell cycle regulation across various cellular models, including cancer, where its knockdown leads to reduced proliferation." (PMID 40636673, 2025). "In recent times, it has been reported that the histone methyltransferase SMYD3 (SET and MYND domain‐containing protein 3) is highly expressed in various human tumors and that overexpression enhances K‐Ras‐associated signaling in cancer cells." (PMID 39286779, 2024). "Thus, based on the emerging role played by the methyltransferase SMYD3 in the regulation of DDR by promoting HR repair and hence cancer cell genomic stability, we performed an in-depth analysis of SMYD3 activity in cancer response to chemotherapy." (PMID 38812026, 2024). "Our current discovery of the novel small molecule targeting SMYD3 may open a new avenue in future cancer treatment." (PMID 39286779, 2024). "On the other hand, SMYD3-KO models, such as cells and xenograft mice models, revealed that SMYD3 genetic ablation reduces cancer cell resistance to CHTs, which is restored by exogenous expression of the WT protein, while the catalytically inactive form fails to do so." (PMID 38812026, 2024).
cancer (continued). "Based on these premises, we generated tumorspheres from the HCT116 CRC cell line and its SMYD3-KO counterpart to evaluate the effect of SMYD3 ablation or pharmacological inhibition on cancer cell proliferation and chemotherapy response in these more complex systems." (PMID 38812026, 2024). "This information points to SMYD3 as a cancer drug discovery and development candidate." (PMID 39286779, 2024). "Additionally, we address the potential of SMYD3 inhibitors as promising strategies for cancer treatment." (PMID 39482529, 2024). "Interestingly, SMYD3 does not appear to be essential for normal development, as previously shown in SMYD3-KO mice, while it is overexpressed in a wide variety of cancers and is therefore involved in the development of these malignancies." (PMID 38812026, 2024). "SMYD3 has been reported to regulate the cell cycle progression of diverse types of human cancers." (PMID 38892227, 2024). "The methyltransferase SMYD3 is a regulator of epigenetic and signaling pathways in cancer and has drawn significant attention from researchers and companies focusing on the identification and targeting of novel factors to develop effective treatment strategies." (PMID 38812026, 2024). "This is due to the correlation observed between SMYD3 overexpression and cancer cell growth in several types of tumors and to SMYD3 oncogenic activity as a transcriptional activator of genes and co-regulator of pathways involved in transformation and cancer progression." (PMID 38812026, 2024). "Inhibiting HSP90 in these cancers can reduce SMYD3 activity, providing another therapeutic target." (PMID 39564119, 2024). "In addition, the novel SMYD3 covalent inhibitor EM127 was used to evaluate the impact of manipulating SMYD3 activity on the sensitization of cancer cell lines, tumorspheres and cancer murine models to chemotherapeutics (CHTs)." (PMID 38812026, 2024). "SMYD3 transactivates multiple oncogenic mechanisms, favoring cancer development." (PMID 38812026, 2024). "Co-targeting SMYD3/PARP leads to synthetic lethality in HR-proficient cancer cells." (PMID 38191478, 2024). "Here we report that SMYD3 mediates cancer cell sensitivity to CHTs." (PMID 38812026, 2024). "Recently, SMYD3 has been shown to play an important role in the regulation of DNA damage checkpoint dynamics in cancer cells by inducing the formation of HR complexes and promoting HR repair in response to genotoxic stress, thereby allowing DSB restoration and hence cancer cell genomic stability." (PMID 38812026, 2024). "The findings suggest that targeting SMYD family members, especially SMYD2 and SMYD3, could be an effective cancer treatment strategy." (PMID 39482529, 2024). "Inhibition of SMYD3 has therapeutic potential for cancer treatment." (PMID 38540216, 2024). "Several previous studies have reported factors that regulate SMYD3 in various cancers." (PMID 39482529, 2024). "Other histone (e.g. H4K5 and H4K20) and non-histone (VEGFR, human epidermal growth factor receptor 2 (HER2), mitogen-activated protein 3 kinase 2 (MAP3K2), estrogen receptor (ER) and others) substrates of SMYD3 have, however, been discovered since this finding, especially in relation to cancer (Ref." (PMID 39320855, 2024). "SMYD3 is considered as an essential regulator of cancer stem cell characteristics." (PMID 37237385, 2023). "Considering that immunotherapy is among the most promising new cancer treatments, confirming the potential of SMYD3 pharmacological blockade may pave the way toward effective translational advances." (PMID 37998381, 2023). "The aberrant overexpression of SMYD3 in multiple cancer types indicates its pro-tumor functions." (PMID 37386026, 2023). "SMYD3 is a member of the SET and MYND Domain (SMYD) lysine methyltransferase family, which includes multi-domain SET methyltransferases implicated in human cancerogenesis, cancer progression, and invasion." (PMID 37954147, 2023).